PRDM16 (PR/SET domain 16)
Diseases named in the same sentence as PRDM16 in open-access papers (continued):
Sharing a sentence is not in itself a finding about the gene and the disease.
cancer (45 papers, 2013 to 2026). A tumor composed of atypical neoplastic, often pleomorphic cells that invade other tissues. "Of note, MECOM and PRDM16 are the most mutated genes in the PRDM family in multiple human cancers, which has been verified to promote the occurrence and progression of acute myeloid leukemia." (PMID 35174083, 2022). "For that reason, we performed WES and identified highly relevant variants in cardiac and cancer genes, such as PRDM16 (p.P878L) in ACT patient 2, and SYNM (p.V1004I), TTN (p.V27642M), and an EGFR (p.E868Nfs*35) variant in ACT-3." (PMID 35260914, 2022). "At present, whether Prdm16 has any role in cancer pathogenesis and progression that is linked to its function in TGF-β signaling is still unknown." (PMID 36828547, 2023). "Although several other members of the PRDM family are associated with cancer especially the PRDM16." (PMID 32662828, 2020). "The most frequency genes are TP73 (both alleles loss) and PRDM16 (high copy gain) both are associated with late cancer stages which may cause uncontrolled cell division due to these genes changes." (PMID 30212456, 2018). "Notably, some of the cancer cell lines with TGFB2 or PRDM16 gene hypomethylation also displayed cancer cell linked promoter hypermethylation." (PMID 25606572, 2014). "It has been reported that PRDM16 knockout in T cells facilitates adoptive immunotherapies for cancer." (PMID 40758676, 2025). "Among them, PRDM16, SETDB2, SGF29, and ZCWPW2 were protective genes and were all downregulated in the tumor samples, while the others were enriched in the cancer tissues and were associated with poor prognosis." (PMID 36263018, 2022). "Here, we identified PRDM16 exhibited antitumor activities toward cancer cell proliferation and migration by its targeting of pyruvate carboxylase and regulating EMT." (PMID 34796170, 2021). "PRDM16 (known as MEL1), a member of the PR domain zinc finger family, has been implicated in multiple biological processes, including cancers." (PMID 34796170, 2021). "Both in vitro and in vivo analyses established that PRDM16 was capable of inhibiting the EMT of cancer cells by repressing the transcription of Mucin-4 (MUC4), one of the regulators of EMT in lung adenocarcinomas." (PMID 32290321, 2020). "These eight transcripts were linked to the following cancer‐related genes: TRIM33, USP6, PRDM16, SETD1B, MLLT3, KEAP1, CHD2, and DCAF12L2." (PMID 32821278, 2020). "Altogether, these findings indicate that PRDM16 methylation status, both hypermethylation and hypomethylation, is often affected in distinct cancers, where this gene can play alternatively a role as an oncogene or as a tumor suppressor gene." (PMID 32290321, 2020). "Compared with other PRDM members, the role of PRDM16 in cancer biology has been poorly studied and remains to be fully elucidated." (PMID 30683132, 2019). "Although the tumor formation rate (5/5, 100%), volume and weight of subcutaneously injected tumors were similar, the invasive ability of cancer cells was decreased in the PRDM16 overexpression group." (PMID 30683132, 2019). "Given that PRDM16 has been reported to function mainly as a transcriptional regulator, we next performed ChIP-sequencing (ChIP-Seq) to identify direct PRDM16 target genes and further investigate the mechanism through which it inhibits cancer cell EMT." (PMID 30683132, 2019). "Specifically, PRDM12 and PRDM13 were largely overexpressed in many cancers whereas PRDM16 and ZFPM2/FOG2 were often downregulated." (PMID 30347759, 2018). "Overall, PRDM2, PRDM3/MECOM, PRDM9, PRDM16 and ZFPM2/FOG2 were the most mutated genes with pan-cancer frequencies of protein-affecting mutations higher than 1%." (PMID 30347759, 2018). "PRDM16 has previously been reported to be involved in myeloid and lymphoid malignancies, and to play a role in the regulation of hematopoietic, neuronal stem cell growth, and differentiation of adipose tissue." (PMID 26559765, 2015).
cancer (continued). "This enhanced inflammatory status or pro-inflammatory profile of the tumor microenvironment has been shown to contribute to increased lipolysis and cancer cachexia in variable types of cancers through PRDM16 gene overexpression via activation of the STAT3 pathway." (PMID 40227577, 2025). "However, PRDM16 regulates other important biological processes beyond adipogenesis, including in the brain, intestine, and cancer." (PMID 41226287, 2025). "Thus, the role of PRDM16 in cancer biology has been poorly studied and remains to be fully elucidated." (PMID 32607130, 2020). "Then, how does PRDM16 regulate the migratory and invasive phenotypes of cancer cells?" (PMID 30683132, 2019). "The malfunction of PRDM16 is related to a poor prognosis of cancer patients." (PMID 27893424, 2017). "In the unclassified subgroup, apart from previously reported mutations in epigenetic regulators in multiple cancers, including KMT2C, KMT2D, KMT2B, PRDM2, NCOR2, KAT6B, and EP300, in this cohort, we also found new recurrent mutations in epigenetic regulators, including CREBBP and PRDM16." (PMID 30950204, 2019). "Dysfunction of the human orthologs of Ham, PRDM16 (Mel1) and PRDM3 (Evi1, MECOM), has been found in a variety of human abnormalities including congenital diseases, metabolic disorders and cancers." (PMID 40613556, 2025). "Collectively, these results indicate that LINC00589 regulates trastuzumab resistance, cancer stem cell-like properties and multiple chemoresistance, at least in part, by modulating DLG5 and PRDM16 expression." (PMID 36309503, 2022). "Although both regulate the expression of UCP-1, PPARγ, PRDM-16, PGC-1α, and other regulatory factors, the effects of nutrients, such as anti-inflammatory, anti-cancer, and anti-oxidation substances, on metabolism are more extensive." (PMID 35886989, 2022). "This analysis shows that the 1CT7 specific mutated genes are altered in 30.4% of all CRC cases whereas A1309 specific mutated genes are altered in 73.6% of all CRC cases, among which five genes are known cancer genes, i.e. PBRM1, MYB, PRDM16, BCR and NUP214." (PMID 25923178, 2015). "Whereas, the function of PRDM16 in the immune response of cancers was not systematically investigated, which needs to be further studied." (PMID 35174083, 2022). "Among these genes, two are oncogenes and also translocated cancer genes (CBFA2T3 and PRDM16)." (PMID 33711952, 2021). "We identified HBV integrations with high integration allele fractions in tumors in seven non-recurrent cancer-related genes, including GAS7, NSP, RSPO2, NRG1, PRDM16, ARID1B, and AFF1." (PMID 33557409, 2021). "Of the oncogenes, three are translocated cancer genes (CBFA2T3, PDGFB and PRDM16)." (PMID 33711952, 2021). "Furthermore, recent studies indicate that TNF-α and IL-6 promote cancer cachexia in different types of cancer, including gastric and CRC, by protein 16 containing PR domain (PRDM16) gene overexpression via the STAT3 signaling pathway, which induces the browning of WAT." (PMID 37760840, 2023). "For instance, PRDM16 functions as a tumor suppressor gene in malignant tumors, and the overexpression of PRDM16 could inhibit EMT by repressing MUC443,44, and MUC4 has been reported to be overexpressed in IMPC45, which is consistent with the losses of PRDM16." (PMID 35013309, 2022). "However, it is also conceivable that Prdm16 might function to suppress metastasis induced by other TGF-β superfamily members, such as Activins and BMPs, which are known to signal through Smad4, and can enhance malignancy and promote cancer metastasis in a variety of human malignancies." (PMID 36828547, 2023). "Among the identified genes, PRDM16 and DLC1 have been studied in various types of cancers, and the significance of these genes in OSCC has not been examined." (PMID 34051764, 2021).
tumor (39 papers, 2009 to 2026). "Cdkn2a (encoding tumour suppressors p14 and p16) and Prdm16 were exclusively expressed by tumours seemingly insensitive to these cell cycle arrest genes given their Ki67+ nature." (PMID 38658753, 2024). "Control of tumor vascularization was reflected in depletion of mutations in PRDM16, which inhibits angiogenesis by suppressing the expression of a HIF target semaphorin 5B, and in NCO1A, a transcriptional coactivator that upregulates the expression of the VEGFα pro-angiogenic factor." (PMID 34307377, 2021). "The PRDM protein family, including members such as PRDM2 and PRDM16, showcases a similar yin-yang paradigm in tumor contents observed in PRDM1, characterized by two functionally antagonistic isoforms originating from a single gene." (PMID 39562537, 2024). "By discovering an antagonistic relationship between the tumor suppressors Prdm16 and Smad4 in PDAC, this study paves the way for innovative frameworks with potential therapeutic implications." (PMID 36828547, 2023). "Collectively, these findings unveil an unprecedented antagonistic interaction between the tumor suppressors Smad4 and Prdm16 that functions to restrict PDAC progression and metastasis." (PMID 36828547, 2023). "To substantiate this finding, we analyzed Prdm16 expression by immunohistochemistry (IHC) using large human tissue microarrays (TMAs) comprising samples with tumor lesions at various stages (e.g., PanIN1, PanIN2, PanIN3, PDAC) and normal tissues." (PMID 36828547, 2023). "We further checked the gene expression in primary tumor versus normal tissue for genes JAK2, PRDM16, LRP1B, NIN, and NKX2-1 with variants repeatedly enriched in variant-based analysis, and, FANCE, enriched in gene-based burden testing, using the TCGA database." (PMID 35954343, 2022). "By contrast, PRDM16 was observed with extensive epigenetic gene silencing and inhibits tumor growth by suppressing HIF-targeted gene semaphorin 5B in renal cancer." (PMID 35174083, 2022). "Seventy-five of 110 PTC patients presented a lower PRDM16 expression level in tumor tissue than that in the paired normal tissue, and only 31.82% patients had a higher PRDM16 expression level in tumor tissue compared with the paired normal tissue." (PMID 34796170, 2021). "Overexpression of PRDM16 significantly slowed the speed of tumor growth and reduced overall tumor weight in vivo." (PMID 34796170, 2021). "PRDM16, which also plays an important role in protein modification, is also closely related to fat metabolism and tumor growth." (PMID 33996555, 2021). "Of note, TCGA gene expression profiling of PRDM genes revealed significant overexpression of PRDM12 and PRDM13 in many tumor types whereas ZFPM2/FOG2, PRDM8, and PRDM16 were more often downregulated in tumor tissues." (PMID 30347759, 2018). "The tumor suppressor miR-101 reverses the hypomethylation status of PRDM16 and suppresses the expression of PRDM16 through direct and epigenetic regulation." (PMID 26701852, 2016). "Two tumors have insertions in the leukemia transcription factor oncogene Prdm16 but only the insertion in tumor 7107 is clonal." (PMID 19461887, 2009). "Low PRDM16 expression is associated with poor survival, providing an initial hint that Prdm16 might function as a tumor suppressor in PDAC." (PMID 36828547, 2023). "Subsequent genetic experiments showed that ablating Prdm16 along with Smad4 resulted in a shift from a well-differentiated and confined neoplasm to a highly aggressive and metastatic disease, which was associated with a striking deviation in the trajectory of the premalignant lesions." (PMID 36828547, 2023). "As such, our findings unveil a previously uncharacterized mechanism that orchestrates Prdm16 tumor-suppressive function, and further shed new insights into the molecular etiology of PDAC, a fatal disease for which no effective therapeutics are currently available." (PMID 36828547, 2023).
tumor (continued). "Using the KrasG12D-based mouse model of human PDAC, we surprisingly found that ablating Prdm16 did not block but instead accelerated PDAC formation and progression, suggesting that Prdm16 might function as a tumor suppressor in this malignancy." (PMID 36828547, 2023). "Taken together, these data suggest that PRDM16 could suppress tumor progression and EMT process via PC." (PMID 34796170, 2021). "The same authors proved that the tumor suppressor miR-101 could reverse the PRDM16 hypomethylation status thus suppressing its expression through direct epigenetic regulation, finally leading to mitochondrial disruption and apoptosis." (PMID 32290321, 2020). "Beyond the well-recognized role exerted by PRDM16 in the differentiation and function of brown and beige fat, the increase in the Warburg effect arising from the downregulation of PRDM16 strongly enforces PRDMs as players in the metabolic reprogramming of tumor growth." (PMID 32290321, 2020). "In addition to the 8 representative PKMTs with tumor suppressor activity, PRDM16, MLL2, MLL4, SET domain bifurcated histone lysine methyltransferase 1 (SETDB1), SETD3, NSD1, NSD3, DOT1L, SUV39H1, and SUV39H2 have also been suggested to possess tumor suppressor activity." (PMID 38036730, 2023). "Because TGF-β signaling activation leads to the accumulation of Prdm16 through the suppression of Smad4 inhibitory effects, one would speculate that Smad4 and Prdm16 might function in the same signaling network that integrates the TGF-β tumor promoter effects during PDAC progression." (PMID 36828547, 2023). "Prdm16 is also insertionally mutated in two of the murine T-ALLs with Lmo2 insertions so this gene's involvement in tumor induction might not be limited to the myeloid lineage." (PMID 19461887, 2009). "It has been reported that PRDM16 represses the transcriptional activity of TGF-β signaling and tumor cell proliferation by binding to p-Smad3 and suppressing the interaction of p-Smad3 with DNA." (PMID 40758676, 2025). "Acting as a ceRNA platform, LINC00589 acts as a sponge for miR-100 and miR-452, thus relieving their suppression of tumor suppressors such as DLG5 and PRDM16." (PMID 37781073, 2023). "In HER2+ breast cancer 24, LINC00589 overexpression significantly decreased tumor volume and weight, inhibited luciferase activity, and upregulated DLG5 and PRDM16 protein expressions." (PMID 37781073, 2023). "To evaluate browning of perirenal AT, we measured mRNA levels of Prdm16, TBX1, Ucp1 and PGC1 alpha in AT from normal and tumor kidney." (PMID 35606546, 2022). "Adaptive browning, regulated by transcriptional drivers such as PRDM16, PPARγ, and PGC1-α, mitigates metabolic inflammation, enhances insulin sensitivity, and may exert tumor-suppressive effects." (PMID 41848823, 2026). "The potential mechanism of MECOM and PRDM16, especially MECOM, in terms of tumor progression, prognosis, and immune cell infiltration in LUAD, however, remains unclear." (PMID 35174083, 2022). "A general differential expression, even though not significant, was observed for both ZFPM2/FOG2 and PRDM16 in several tumor tissues." (PMID 30347759, 2018). "We confirmed that SETDB2 (HR: 0.773, 95%CI: 0.640–0.932), SGF29 (HR: 0.918, 95%CI: 0.860–0.979), PRDM16 (HR: 0.891, 95%CI: 0.807–0.983), CBX7 (HR: 0.906, 95%CI: 0.833–0.986), and ZCWPW2 (HR: 0.325, 95%CI: 0.117–0.901) were protective genes, and they were all downregulated in the tumor samples." (PMID 36263018, 2022). "Luciferase and ChIP assays indicated that PRDM16 exhibits antitumor activities in PTC as a transcription factor through binding to PC promoter, thus inhibiting PC promoter activity at the transcriptional level and further suppressing the EMT process of PTC tumor cells." (PMID 34796170, 2021).
tumor (continued). "Moreover, IHC assay data in xenograft tumor tissues revealed that LINC00589 overexpression could upregulate the protein expressions of DLG5 and PRDM16, while miR-100 and miR-452 abrogated the promotion of LINC00589 on the DLG5 and PRDM16, respectively." (PMID 36309503, 2022). "However, the role of PRDM16 in tumor biology has not been well addressed." (PMID 30683132, 2019).
metabolic disease (8 papers, 2023 to 2025). A congenital disorder (due to inherited enzyme abnormality) or acquired (due to failure of a metabolically important organ) disorder resulting from an abnormal metabolic process. "It will be interesting to see if the PRDM16-SREBP1/2 axis is a valid therapeutic target in metabolic disease." (PMID 41226287, 2025). "The current revelation of androgen in negative modulation of PRDM16 would potentially provide a good therapeutic window for anti‐obese and anti‐metabolic disease drugs targeting PRDM16." (PMID 37211698, 2023). "Furthermore, PRDM16 has been identified as a key activator of beige adipocyte biogenesis, conferring protection against metabolic disorders." (PMID 41420191, 2025). "Thus, the different interactions involving PRDM16 have emerged as potential targets in metabolic disease." (PMID 41226287, 2025).
cardiovascular disease (7 papers, 2022 to 2026). "Here we identify PRDM16, a gene linked to cardiovascular disease, as a critical transcriptional repressor of the synthetic SMC phenotype." (PMID 41107595, 2025). "In this review, we give a synopsis of PRDM16's expression and function within (developing) cardiovascular tissues and provide insights into how impaired PRDM16 signalling contributes to cardiovascular disease." (PMID 40439125, 2025). "SMC-deficiency of Prdm16 does not affect the aortic morphology at baseline but significantly alters expression of many genes involved in VSMC homeostasis and cardiovascular disease, and suppresses VSMC proliferation and neointima formation in male mice." (PMID 41667033, 2026).
hematological malignancies (3 papers, 2011 to 2021). "Genes highlighted here in, such as PRDM16, PER3, NOM1 BAHCC1, ZNF423, SETD7, RPTOR, and others have been implicated in hematological disease development, progression or clinical outcome." (PMID 34200630, 2021). "In conclusion, using FISH, we characterized the breakpoints on 1p36 in 81 cases of hematological malignancies with cytogenetic 1p36 alterations not affecting the PRDM16 locus and showed that the breakpoints were more widely distributed than previously reported." (PMID 22039459, 2011).
infection (3 papers, 2023 to 2025). The state of being infected such as from the introduction of a foreign agent such as serum, vaccine, antigenic substance or organism. "Infection of wild-type primary NSCs with this construct yielded a cell line with robust Prdm16 mRNA expression and detectable nuclear PRDM16 protein, which we referred to as Prdm16_overexpressing (Prdm16_OE)." (PMID 40658097, 2025). "Decreased expression of Prdm16 promotes type 17 immunity gene expression program and lipid-dependent cell fitness, which in turn increases the generation of inducible Vγ4+ γδT17 cells that can respond to infection." (PMID 38239368, 2023).
cardiac disease (2 papers, 2024 to 2025). "As a transcription factor, PR domain‐containing 16 (PRDM16), has recently been implicated in brown fat biogenesis and heart diseases." (PMID 39309696, 2024).
neurodegenerative disease (2 papers, 2024). A disorder of the central nervous system characterized by gradual and progressive loss of neural tissue and neurologic function. "Additionally, PRDM16 mutations and altered PRDM16 expression have been linked to neurodegenerative diseases highlighting its role in neural stem cell maintenance and differentiation." (PMID 39765675, 2024).
hematologic neoplasm (1 paper, 2021). "Apart from the study in hematologic neoplasm, recent research has explored controversial functions of the PRDM16 gene in solid cancers." (PMID 34796170, 2021).